CBS (cystathionine beta-synthase)
Diseases named in the same sentence as CBS in open-access papers (continued):
Sharing a sentence is not in itself a finding about the gene and the disease.
Stroke (25 papers, 2009 to 2025). Sudden impairment of blood flow to a part of the brain due to occlusion or rupture of an artery to the brain. "There is limited research on methionine synthase (MS) and cystathionine beta-synthase (CBS) gene polymorphisms among stroke patients in Southeast Asia." (PMID 40718281, 2025). "The table shows that hyper methylation of the CBS promoter gene increases the risk of hypertension and stroke." (PMID 37900914, 2023). "A domestic meta-analysis provided evidence that CBS T833C genetic polymorphism was associated with the risk of stroke." (PMID 37039942, 2023). "Nevertheless, the results from subgroups of the Chinese and Caucasian populations are different; in the Chinese subgroup, the results showed that CBS T833C polymorphism leads to increased incidences of stroke." (PMID 37039942, 2023). "Other evidence has shown that the genetic polymorphism of an enzyme involved in the conversion of Hcy to Cys (cystathionine β-synthase (CBS) T833C) is associated with severe forms of HHcy and an increased risk for subacute thrombosis and subsequent stroke." (PMID 35054087, 2022). "For example, researchers set out to investigate the association of cysteine, a downstream product of the CBS pathway and upstream substrate of H2S production, and its association with impaired outcomes in situations of ischemia and stroke." (PMID 33212887, 2020). "Hypermethylation of CBS leads to low enzyme activity, plasma homocysteine accumulation, and increased susceptibility to stroke." (PMID 31941075, 2020). "At present, many studies have explored the relationship between CBS mutations and stroke, of which T833C point mutation is the most common." (PMID 33138824, 2020). "This matched case-control study aimed to investigate the relationship between CBS methylation and the risk of hypertension and stroke in a Chinese population." (PMID 30916171, 2019). "Yet, the CBS-deficient patients exhibited a pro-stroke proteomic signature that was very similar to the proteomic signature of the ischemic stroke patients, each of whom suffered an ischemic stroke immediately before participation in the study." (PMID 31242583, 2019). "To identify biological pathways linked to proteins affected by CBS deficiency or stroke subtype, we carried out bioinformatic analyses using IPA resources." (PMID 31242583, 2019). "The top four highly significant (−log(p-value) = 20–31) pathway categories affected by both CBS deficiency and stroke subtypes were LXR/RXR activation, acute phase response signaling, FXR/RXR activation, and coagulation system." (PMID 31242583, 2019). "Association of CBS methylation and the risk of hypertension and stroke adjusted by multivariable logistic regression models." (PMID 30916171, 2019). "ROC curves were generated to evaluate the role of the PMR level of CBS in the diagnostic value of hypertension and stroke." (PMID 30916171, 2019). "The results revealed that CBS promoter hypermethylation was an independent risk factor for hypertension and stroke, especially in men." (PMID 30916171, 2019). "The purpose of the present matched study was to examine the risk of abnormal CBS methylation in hypertensive and stroke patients." (PMID 30916171, 2019). "Multivariable logistic regression analysis indicated that CBS promoter hypermethylation significantly increased the risk of hypertension and stroke, and the ORs (95% CI) were 1.035 (1.025–1.045) and 1.015 (1.003–1.028), respectively." (PMID 30916171, 2019). "We found that proteins affected by CBS deficiency were significantly enriched in 13 molecular pathways, while proteins affected by stroke subtypes were similarly enriched in the same molecular pathways." (PMID 31242583, 2019). "This conclusion is consistent with findings of other investigators showing that CBS-deficient patients are prone to the embolic stroke." (PMID 31242583, 2019). "The cystathionine-beta-synthase (CBS) gene has been associated with stroke and methionine metabolism." (PMID 24651765, 2014).
Stroke (continued). "A meta‐analysis provided evidence that CBS T833C gene polymorphisms were associated with stroke risk; however, the results differed between the Chinese and Caucasian subgroups, and in the Chinese subgroup, the results showed that CBS T833C gene polymorphisms led to an increased incidence of stroke." (PMID 40612136, 2025). "However, there is limited research on MS and CBS gene polymorphisms among stroke patients in South Asia." (PMID 40718281, 2025). "Interestingly, CBS, via its product cystathionine, has actually been positively associated with risk of stroke." (PMID 33212887, 2020). "However, we adjusted for age by multivariable logistic regression analysis and confirmed that the PMR level of CBS was an independent risk factor both in hypertension and stroke." (PMID 30916171, 2019). "Second, only the PMR level of the CBS gene was measured, and DNA methylation of other genes involved in Hcy metabolism may also confer susceptibility to hypertension and stroke." (PMID 30916171, 2019). "Similar molecular networks centering on NFκB were affected by CBS deficiency and stroke subtypes." (PMID 31242583, 2019). "Additionally, the CBS promoter hypermethylation increased the risk of hypertension and stroke, especially in male patients." (PMID 31252610, 2019). "Firstly, the differentiating proteins identified in the present study may promote stroke or be a feature present in patients with CBS deficiency and in patients with ischemic stroke." (PMID 31242583, 2019). "In addition, the validity of our study is supported by the findings that many differentiating proteins were shared between the stroke subtypes part and the CBS-deficiency part of the study, which did have a healthy, age- and sex-matched group as a reference." (PMID 31242583, 2019). "The dysregulated proteostasis involving pro-thrombotic N-Hcy-fibrinogen and other proteins participating in blood coagulation could contribute to the pro-thrombotic phenotype of CBS-deficient patients and explain why they are prone to have a stroke at a young age." (PMID 39859460, 2025). "However, results may be influenced by the fact that some of the tested CBS-deficient individuals had a prior history of stroke and thus proteome alterations may have already occurred as a result of the prior ischemia." (PMID 33212887, 2020). "However, even though its CBS deficiency may be related, its role in the development of stroke is unclear." (PMID 33212887, 2020). "Hypermethylation levels of the CBS gene were observed in hypertension and stroke patients, which might lead to silencing of CBS gene expression and accumulation of Hcy levels, thus contributing to the susceptibility to hypertension and stroke." (PMID 30916171, 2019). "CBS promoter hypermethylation increased the risk of male hypertensive patients (OR=1.057; 95% CI = 1.041–1.073), male stroke patients (OR: 1.028; 95% CI: 1.011–1.044), female hypertensive patients (OR: 1.011; 95% CI: 0.996–1.026) and female stroke patients (OR: 0.992; 95% CI: 0.970–1.015)." (PMID 30916171, 2019). "Additionally, N-homocysteinylation can play a role in atherothrombosis through the accumulation of prothrombotic N-Hcy-fibrinogen in CBS-deficient patients and the accumulation of IgG anti-N-Hcy-protein autoantibodies in cardiovascular disease and stroke patients." (PMID 24350259, 2013). "The importance of 1C metabolism can also be seen by the increases in MTHFD1, SHMT, TS, and CBS in both stroke females and males in the present study." (PMID 40950018, 2025). "For instance, H2S production via CBS is greatly elevated following stroke and inhibitors of CBS activity reduced infarct volume in rat models of stroke, whereas administration of H2S-donating compounds increased infarct volume." (PMID 34613340, 2021). "More recently, changes of CBS promoter methylation levels in hypertensive and stroke patients as compared to a healthy population." (PMID 33212887, 2020).
Stroke (continued). "ROC curve analysis also suggested that CBS promoter hypermethylation was a potential biomarker in male subjects for the diagnosis of hypertension and stroke." (PMID 30916171, 2019). "Multivariate-adjusted odds ratios and 95% confidence intervals of hypertension and stroke for CBS methylation in subgroups." (PMID 30916171, 2019). "The AUC of CBS promoter methylation was 0.844 (95% CI, 0.796–0.892) in male hypertensive patients and 0.722 (95% CI, 0.653–0.799) in male stroke patients." (PMID 30916171, 2019). "Some of the stroke subtype-specific proteins (FBLN1, F2, SERPINF2, CBP2, FCN3, GPX3, IKG, and GSN) were also affected by the CBS deficiency." (PMID 31242583, 2019). "However, a direct association between CBS methylation and hypertension and stroke remains unclear." (PMID 30916171, 2019). "Other SNPs in genes involved in inflammation (APOE and IL6), oxidative stress (NOS3 and SOD2), and As metabolism (AS3MT, CBS, GSTO1, and MTHFR) showed nominally significant interactions with well-water As for associations with CVD, CHD, or stroke." (PMID 25575156, 2015). "Among these, three are likely monogenic causes of stroke (ELN, SCN5A, and VHL genes), two are considered risk factors (FV and ADAMTS13), two have conflicting interpretations (ACAD9 and ENG), and three are most likely benign (CBS, PMM2, and PKD1)." (PMID 40650005, 2025). "In conclusion, it seems that the mutations detected in the CBS gene in our patients were not the cause of vascular abnormalities and stroke." (PMID 40650005, 2025). "This study showed that hydrogen-rich saline ameliorates cell injury through up-regulating the expression of CBS in the hippocampus after cerebral ischemia reperfusion (I/R) in rats, this provides new experimental evidence for the treatment of stroke with hydrogen saline." (PMID 32489564, 2020). "So, up-regulating the expression of CBS to promote H2S synthesis may be a therapeutic strategy for stroke." (PMID 32489564, 2020). "The association between AHCY and CBS promoter methylation and stroke studies has not been reported so far." (PMID 33138824, 2020). "Specifically, a study examining the effects of methylation on the development of hypertension and stroke (stroke n = 132, hypertension n = 243, controls n = 218) has found that hypertensive and stroke patients had higher methylation levels in the CBS gene promoter compared with healthy controls." (PMID 31252610, 2019). "The CBS promoter methylation levels of male subjects in the healthy control, hypertensive and stroke groups were significantly different (mean PMRs were 17.50%, 47.70%, and 32.18%, respectively, p<0.001), and those of female subjects were not significantly different (p=0.142)." (PMID 30916171, 2019). "In Chinese Han males, CBS hypermethylation in the blood might serve as an independent biomarker for the diagnosis of hypertension and stroke." (PMID 30916171, 2019). "In conclusion, male patients with hypertension and stroke had increased CBS methylation levels." (PMID 30916171, 2019). "Hence, we provide evidence that upregulation of CBS expression exacerbates the outcome of stroke most likely through increased H2S production." (PMID 25873304, 2015). "Whether and how strokes in CBS-deficient patients are related to strokes in the general population is not known." (PMID 31242583, 2019). "Furthermore, our findings that over half (22 of 40) of differentiating proteins were shared between CBS-deficient and ischemic stroke patients indicate that these proteins are associated with stroke rather than with age." (PMID 31242583, 2019). "In addition, the PMR level of CBS was lower in stroke patients than hypertensive patients." (PMID 30916171, 2019). "CBS may be a potential therapeutic target for the treatment of stroke." (PMID 25873304, 2015). "Therefore, suppression of H2S production via the inhibition of CBS activity may be an attractive approach to improve stroke outcome during the acute phase of ischemic stroke." (PMID 25873304, 2015).
Stroke (continued). "Therefore, CBS inhibition may be a viable approach to stroke treatment." (PMID 25873304, 2015). "SPRC (ZYZ-802), by modulating CBS, reduces astrogliosis, Aβ deposition, and inflammation in Alzheimer’s disease via NF-κB/MAPK, inhibiting TNF-α, COX-2, and ERK1/2, and enhancing microglial migration through CD24 and Src/Fak/Pyk2, effects comparable to those in stroke and neuroinflammation." (PMID 41465271, 2025). "Therefore, the mechanism could be owing to the regulation of CBS by SPRC with the promoted expression of H2S in brain tissue, and H2S further stimulated the expression of CD24 and ultimately alleviated stroke diseases." (PMID 39953809, 2025).
Down syndrome (23 papers, 2008 to 2026). "In a study, genetic overexpression of CBS in the brain resulted in disruptions in serotonin and dopamine pathways, contributing to neuronal disorders associated with Down syndrome." (PMID 39148948, 2024). "Overexpression in Down Syndrome increases the risk of Acute Myeloid Leukemia, indicating a significant link between CBS activity and leukemia." (PMID 39062461, 2024). "The relevance of CBS in the context of human diseases is increasingly recognized, particularly its association with an elevated risk of leukemia in children with Down Syndrome (DS) and its correlation with atherosclerosis in DS patients." (PMID 39062461, 2024). "Because CBS is located on chromosome 21, it was naturally assumed that the cause of the elevation of H2S levels was a “gene dosage” effect: the extra chromosome encodes extra CBS enzyme in the cells and tissues of Down syndrome individuals." (PMID 32340322, 2020). "As discussed in the subsequent chapter, CBS overexpression and H2S overproduction is re-emerging as potential causative factors in the pathogenesis of Down syndrome." (PMID 32365821, 2020). "CBS level is found to be threefold higher in the brains of Down’s syndrome patients than in the normal people but CBS allele expression is lower in children with high intelligence quotient." (PMID 32477150, 2020). "The CBS gene is encoded on chromosome 21 (21q22.3), which is associated with trisomy in Down syndrome (DS)." (PMID 31657521, 2019). "While in classical HCU, the mutated CBS may result in defective transsulfuration, the extra chromosome 21 in Down syndrome results in a higher dose of expression of CBS (as the gene lies on chromosome 21), and hence enhanced transsulfuration." (PMID 37605676, 2023). "For example, Down syndrome patients (trisomy 21) excrete unusually high thiosulfate levels, reflecting elevated CBS activity and H2S production." (PMID 40998690, 2025). "Enzyme CBS is localized to human chromosome 21 whereby in patients with Down syndrome, CBS levels were found to be 1.5‐fold greater compared to those in healthy individuals." (PMID 40829894, 2025). "In subjects with Down syndrome who overexpress CBS and H2S, the urinary levels of TMS are more sensitive to endogenous H2S than the traditional biomarker thiosulfate." (PMID 39643979, 2024). "Elevated CBS expression in certain leukemia types, especially Down Syndrome-related AML, enhances sensitivity to specific chemotherapy drugs." (PMID 39062461, 2024). "Increased H2S due to CBS upregulation has been observed to have an impact on mental impairment and has been indicated to affect the cognitive phenotype in Down syndrome." (PMID 39148948, 2024). "For instance, the triplicated gene for cystathionine β-synthase (CBS) on chromosome 21 in Down syndrome increases H2S levels throughout the body, which suppresses complex IV of the mitochondrial electron transport chain." (PMID 37237961, 2023). "Overexpression of the transsulfuration enzyme cystathionine-β-synthase (CBS), and overproduction of its product, hydrogen sulfide (H2S) are recognized as potential pathogenetic factors in Down syndrome (DS)." (PMID 35921774, 2022). "Aberrant upregulation of CBS and overproduction of H2S contribute to pathophysiology of several diseases including cancer and Down syndrome." (PMID 35864237, 2022). "Intriguingly, a recent publication reported that overproduction of H2S by increased mitochondrial-localized CBS expression results in suppression of mitochondrial oxidative phosphorylation and ATP production in the fibroblasts from Down syndrome patients." (PMID 35758651, 2022). "H2S clearly has the capacity to suppress mitochondrial function (as previously shown for CBS-derived H2S in Down syndrome)." (PMID 32340322, 2020). "Several lines of data indicate that an important enzyme responsible for H2S overproduction in Down syndrome is cystathionine-β-synthase (CBS), an enzyme localized on chromosome 21." (PMID 32340322, 2020).